PCDHA11 (protocadherin alpha 11)
Description:
Potential calcium-dependent cell-adhesion protein. May be involved in the establishment and maintenance of specific neuronal connections in the brain.
Synonyms: CNRS7; CNR7; CRNR7; CNRN7; PCDH-ALPHA11
Tractability: Antibody: its Gene Ontology location is reachable by antibodies, with high confidence; UniProt places it where antibodies can reach, with medium confidence; UniProt predicts a signal peptide or a membrane-spanning region. PROTAC: its protein half-life has been measured.
Gene: Protein-coding gene on chromosome 5 (140,868,183 to 141,012,347, forward strand). Ensembl gene ENSG00000249158.
Subcellular location: Cell membrane
Subcellular location (Human Protein Atlas): Cell Junctions; Vesicles; Cytoplasmic bodies
Gene Ontology:
Molecular function: cell adhesion molecule binding; calcium ion binding
Biological process: cell adhesion; nervous system development; homophilic cell-cell adhesion
Cellular component: plasma membrane; membrane
Genetic constraint (gnomAD): Loss-of-function variants: 61 observed, 73.2 expected, observed/expected ratio (o/e) 0.83, 90% interval 0.68 to 1.03. The upper end of that interval is the gene's LOEUF score, 1.03, which puts it in group 4 of 6, group 1 being the genes least tolerant of losing a copy. Missense variants: 1,324 observed, 1,311.9 expected, observed/expected ratio (o/e) 1.01, 90% interval 0.96 to 1.06. Synonymous variants: 633 observed, 590.48 expected, observed/expected ratio (o/e) 1.07, 90% interval 1 to 1.14.
Homologues: Orthologues: mouse Pcdha11 (85% identical), guinea pig PCDHA11 (65% identical). Paralogues in human: PCDHA8 (81% identical), PCDHA1 (81% identical), PCDHA6 (81% identical), PCDHA2 (81% identical), PCDHA3 (81% identical), PCDHA10 (81% identical), PCDHA13 (81% identical), PCDHA4 (81% identical), PCDHA12 (80% identical), PCDHA7 (80% identical), PCDHA5 (79% identical), PCDHA9 (79% identical), and 49 more.